ACVR1C (activin A receptor type 1C)
Description:
Serine/threonine protein kinase which forms a receptor complex on ligand binding. The receptor complex consists of 2 type II and 2 type I transmembrane serine/threonine kinases. Type II receptors phosphorylate and activate type I receptors which autophosphorylate, then bind and activate SMAD transcriptional regulators, SMAD2 and SMAD3. Receptor for activin AB, activin B, activin E and NODAL. Upon NODAL binding, activation results in increased apoptosis and reduced proliferation through suppression of AKT signaling and the activation of Smad2-dependent signaling pathway in pancreatic beta-cells, trophoblasts, epithelial or neuronal cells. Acts as a positive regulator for macrophage activation partially through down-regulation of PPARG expression (By similarity).
Synonyms: ALK7; ACVRLK7
Tractability: Small molecule: it belongs to a druggable protein family. Antibody: its Gene Ontology location is reachable by antibodies, with high confidence; UniProt predicts a signal peptide or a membrane-spanning region. PROTAC: ubiquitination databases record sites on it.
Target class: TKL protein kinase group; TKL protein kinase STKR1; TKL protein kinase STKR family; Protein Kinase; Enzyme; Kinase
Gene: Protein-coding gene on chromosome 2 (157,526,767 to 157,628,885, reverse strand). Ensembl gene ENSG00000123612.
Subcellular location: Membrane
Pathways (Reactome):
Developmental Biology: Regulation of signaling by NODAL; Signaling by NODAL
Signal Transduction: Signaling by Activin
Gene Ontology:
Molecular function: activin receptor activity; activin receptor activity, type I; growth factor binding; nodal binding; metal ion binding; protein serine/threonine kinase activity; ATP binding; protein kinase activity; transmembrane receptor protein serine/threonine kinase activity
Biological process: apoptotic nuclear changes; apoptotic signaling pathway; cell differentiation; negative regulation of chorionic trophoblast cell proliferation; negative regulation of trophoblast cell migration; nodal signaling pathway; positive regulation of apoptotic process; trophectodermal cell proliferation; activin receptor signaling pathway; cellular response to growth factor stimulus; nervous system development; protein phosphorylation; cell surface receptor protein serine/threonine kinase signaling pathway; regulation of cell migration; regulation of multicellular organismal process; transforming growth factor beta receptor superfamily signaling pathway
Cellular component: activin receptor complex; membrane; plasma membrane; receptor complex
Genetic constraint (gnomAD): Loss-of-function variants: 22 observed, 52.36 expected, observed/expected ratio (o/e) 0.42, 90% interval 0.3 to 0.6. The upper end of that interval is the gene's LOEUF score, 0.6, which puts it in group 2 of 6, group 1 being the genes least tolerant of losing a copy. Missense variants: 474 observed, 606.6 expected, observed/expected ratio (o/e) 0.78, 90% interval 0.72 to 0.84. Synonymous variants: 211 observed, 217.25 expected, observed/expected ratio (o/e) 0.97, 90% interval 0.87 to 1.09.
Homologues: Orthologues: chimpanzee ACVR1C (99% identical), macaque ACVR1C (99% identical), rabbit ACVR1C (98% identical), pig ACVR1C (97% identical), rat Acvr1c (93% identical), mouse Acvr1c (93% identical), guinea pig ACVR1C (92% identical), dog ACVR1C (89% identical), tropical clawed frog acvr1c (77% identical), zebrafish acvr1c (69% identical), Drosophila melanogaster babo (53% identical), Drosophila melanogaster tkv (46% identical), and 2 more. Paralogues in human: TGFBR1 (67% identical), ACVR1B (65% identical), BMPR1B (49% identical), BMPR1A (49% identical), ACVR1 (48% identical), ACVRL1 (45% identical), ACVR2B (31% identical), ACVR2A (31% identical), TGFBR2 (29% identical), BMPR2 (28% identical), AMHR2 (27% identical).
Diseases named in the same sentence as ACVR1C in open-access papers:
ACVR1C is named in the same sentence as 55 diseases in open-access papers, as found by Europe PMC text mining. Sharing a sentence is not in itself a finding about the gene and the disease. The quoted sentences say what the papers report.
Obesity (12 papers, 2009 to 2025). Accumulation of substantial excess body fat. "With regards to risks vis-a-vis benefits of ALK7 inhibition in therapeutic approaches to obesity, the fact that human carriers of ACVR1C variants were otherwise healthy is encouraging." (PMID 38307384, 2024). "Together, these results indicate that in mice of C57BL/6J genetic background, the I195T ACVR1C variant is recessive and can only affect fat accumulation and diet-induced obesity when present in homozygous form." (PMID 38307384, 2024). "•Mice carrying I195T variant from human ACVR1C gene showed resistance to high fat diet (HFD)-induced obesity." (PMID 38307384, 2024). "Gene ACVR1C is highly expressed in adipose tissue, and has been associated to extraocular retinoblastoma, hyperkeratosis, T2DM, obesity and anthropometric measurements, such as waist-to-hip ratio and body mass index." (PMID 37033211, 2023).
type 2 diabetes (6 papers, 2020 to 2024). "Interestingly, variants of the ALK7 (ACVR1C) gene in humans leads to similar phenotypes (favorable fat distribution and protection from type 2 diabetes) as those shown in variants of the INHBE gene." (PMID 38533769, 2024). "In the comparison of the CP and Ba groups, the upregulated gene ACVR1C is known to promote the proliferation of retinoblastoma, increase the prevalence of type II diabetes, and reduce fat content." (PMID 38891594, 2024). "Genes such as KCNE2, DLL1, ACVR1C, RGS3, MLXIPL (MLX interacting protein like), PAG1, SLC2A10 and GRB14 play important role in type 2 diabetes mellitus progression." (PMID 33902539, 2021).
diabetes (5 papers, 2017 to 2025). "Three human ACVR1C variants harboring missense mutations in the receptor intracellular domain were recently associated with a reduced waist to hip ratio and resistance to diabetes, which indicates that the ALK7 signaling pathway serves a metabolic role that is conserved between rodents and humans." (PMID 36626233, 2023).
colorectal cancer (4 papers, 2014 to 2024). A primary or metastatic malignant neoplasm that affects the colon or rectum. "In a cancer stem cells enriched colorectal cancer spheroid cell model, ACVR1C was described as one of the six key molecules involved in signaling pathways for controlling various aspects of cancer stem cells." (PMID 38558282, 2024). "ACVR1C down-regulation in colorectal cancer was reported in several studies." (PMID 31973134, 2020).
retinoblastoma (4 papers, 2019 to 2024). A malignant tumor that originates in the nuclear layer of the retina. "They found a three-fold increase of the receptor ACVR1C in invasive retinoblastomas, which invaded the optic nerve compared to non-invasive tumors." (PMID 36497295, 2022). "We previously found that the ACVR1C/SMAD2 pathway is significantly upregulated in invasive retinoblastoma samples from patients." (PMID 31451106, 2019). "In our previous study we demonstrated that genetic and pharmacological blockade of the Activin A receptor type 1C (ACVR1C), also known as Activin-like kinase receptor 7 (ALK7), strongly inhibited both primary growth and metastatic spread of retinoblastoma cells." (PMID 31451106, 2019). "The inhibition of ACVR1C/SMAD2 pathway using a selective inhibitor of ALK4/5/7 receptors, or down-regulation of ACVR1C or SMAD2 by shRNAs, suppressed retinoblastoma cells lines derived from primary tumors or vitreous." (PMID 35954181, 2022). "We have recently demonstrated a crucial role for ACVR1C/ALK7, a type I receptor of the TGF-β family ligands, in promoting an aggressive phenotype in retinoblastoma." (PMID 31451106, 2019). "Here we focused on the role of an ACVR1C/ALK7 ligand, Nodal, to determine whether modulation of expression might impact downstream signaling as well as metastatic behavior of the retinoblastoma cells." (PMID 31451106, 2019).
breast carcinoma (3 papers, 2020 to 2023). "Previous reports also suggest that both GLI1 and ACVR1C are down-regulated in breast cancer." (PMID 31973134, 2020). "In summary, a shift in the expression pattern of BMPs in breast cancer, including increased BMP8A, BMPR1B and decreased BMP6, BMP7, ACVR1C, TGFBR2, TGFBR3 and BMPR2 presented a subtype specific role." (PMID 37333824, 2023).
Hepatic steatosis (2 papers, 2023 to 2025). Steatosis is a term used to denote lipid accumulation within hepatocytes. "In contrast, the ACVR1C gene is linked to “hepatic steatosis”, “glucose metabolism disorder”, and the canonical pathway’s “TGF-b signaling”, “WNT/b-catenin signaling”, and “PPARa/RXRa activation pathway”." (PMID 37511368, 2023).
lung carcinoma (2 papers, 2020 to 2021). "Most BMPs/BMP receptors were downregulated in lung cancer tissues, except BMP7, ACVR1C, and ACVR2B which were upregulated in one dataset." (PMID 34036102, 2021). "ACVR2A, ACVR1C, BMP4, and CHRDL2, on the other hand, was found to be commonly co-expressed with BMP5 in bladder, breast and lung cancer." (PMID 31973134, 2020).
Alzheimer disease (1 paper, 2024). A progressive, neurodegenerative disease characterized by loss of function and death of nerve cells in several areas of the brain leading to loss of cognitive function such as memory and language. "Given misregulation of the TGF-β pathway that occurs with age and in Alzheimer’s Disease (AD) patients, we first examine whether Acvr1c declines with age in mouse and human hippocampus." (PMID 38714691, 2024).
anxiety disorder (1 paper, 2012). A category of psychiatric disorders which are characterized by anxious feelings or fear often accompanied by physical symptoms associated with anxiety. "Our study indicates that four genes related to neuropathic syndrome, stress, anxiety disorders and depression (Acvr1c, Cort, Htr2b and Pnoc) may have impaired response to stroke in aged rats." (PMID 23251410, 2012).
breast tumours (1 paper, 2023). "ACVR1C, TGFBR2, TGFBR3, ACVR2A, ACVR1, BMPR1A and BMPR2 were lower in breast tumours while ACVR1B and BMPR1B exhibited relatively higher expression levels in paired tumours compared with normal breast tissues, in the TCGA_BRCA cohort." (PMID 37333824, 2023).
meningioma (1 paper, 2016). A generally slow growing tumor attached to the dura mater.
metastatic disease (1 paper, 2024). "In conclusion, the presented work identified the seven genes EMILIN3, MTA1, SV2B, TMPRSS6, ACVR1C, NFAT5 and SMC3 associated with the formation of colorectal BM during the course of disease but not with liver metastasis or non-metastatic disease." (PMID 38558282, 2024).
psoriasis (1 paper, 2021). An autoimmune condition characterized by red, well-delineated plaques with silvery scales that are usually on the extensor surfaces and scalp. "Activin A receptor type 1C (ACVR1C), a type I transforming growth factor-β (TGF-β) receptor, has been implicated in sensitive skin and psoriasis and is involved in the regulation of metabolic homeostasis as well as cell proliferation and differentiation." (PMID 33499275, 2021). "ACVR1C is expressed in human skin, and its expression is decreased in sensitive skin and psoriasis." (PMID 33499275, 2021).
rectum adenocarcinoma (1 paper, 2020). An adenocarcinoma arising from the rectum. "The analysis showed that BMP5 was significantly co-expressed with ACVR1C in mixed lobular and ductal breast, invasive lobular breast, colon, rectal mucinous, cecum mucinous and rectum adenocarcinoma." (PMID 31973134, 2020).
Stroke (1 paper, 2012). Sudden impairment of blood flow to a part of the brain due to occlusion or rupture of an artery to the brain. "Of these Cort, which is also involved in sleep homeostasis remained downregulated on day14 post-stroke in both age groups, and Acvr1c, Htr2b and Fstl1 all involved in pain response, remained high at day14 in aged rats." (PMID 23251410, 2012).
uterine tumors (1 paper, 2023). "ACVR1B and ACVR1C were also mutated in uterine tumors, showing ~34 and 31 mutations each." (PMID 36906706, 2023). "We profiled the data from uterine tumors deposited to the cBioPortal of Cancer Genomics for mutations of the TGFβ signaling pathway and identified several mutations in TGFβ-related receptors (TGFBR1, TGFBR2, ACVR1B, ACVR1C, ACVR2A, ACVR2B) and transcription factors (SMAD2, SMAD3, SMAD4)." (PMID 36906706, 2023).
tumor (12 papers, 2014 to 2025). "Increased expression of ACVR1C seems to be associated with a less aggressive tumor growth and high ACVR1C expression was a positive prognostic factor in several tumor entities." (PMID 38558282, 2024). "Acvr1c mRNA was most abundant in basophils, followed by tumor and NK cells, but below detection in fibroblasts." (PMID 38304252, 2023). "Interestingly, expression of ACVR1C was negatively associated with let-7i expression in only the LNP group, suggesting that these tumours may have gone through the conversion." (PMID 29588449, 2018). "This may suggest the correlation between ACVR1C expression and HDAC10 modulation in SS and highlights the possible tumor suppressor nature of the activin signaling pathway." (PMID 39958888, 2025). "In contrast, PD-PDX kinases with potential to be restored by the addition of MSCs include ACVR1C (ALK7), MAP3K14 and ROR1, which may be inhibitors of tumour growth, and JAK1, involved in the STAT3 signalling pathway characteristic of the inflammatory molecular subclass of CCA." (PMID 39492622, 2024).
cancer (8 papers, 2020 to 2025). A tumor composed of atypical neoplastic, often pleomorphic cells that invade other tissues. "Examples of potentially anti-proliferative pathways activated by paracrine signalling include those involving ACVR1C, MAP3K14 and ROR1, linked to inhibition of cancer growth including in the context of CCA." (PMID 39492622, 2024). "Among the PPI proteins, six kinases were found to be associated with cancer pathways, including mTOR complex 1 (mTORC1), Janus kinase 1 (JAK1), Activin receptor type 1C (ACVR1C), Phosphorylase kinase catalytic subunit gamma 1 (PHKG1) and mitogen-activated protein kinase 4 (MAPK4)." (PMID 37355516, 2023).
cardiovascular disease (2 papers, 2017 to 2022). "The gene ACVR1C (activin A receptor type 1C) studied in 2015 with high BWI value 1547.5 is a member of TGF-beta receptors and is reportedly correlated in expression with pathogenic risk of T2DM as well as cardiovascular diseases." (PMID 28761062, 2017). "Phenotypic follow-up suggests that LoF of PLIN1, PDE3B, and ACVR1C favorably affects metabolic phenotypes (eg, triglycerides [TGs] and high-density lipoprotein [HDL] cholesterol concentrations) and reduces the risk of cardiovascular disease, whereas PLIN4 LoF has adverse health consequences." (PMID 34875679, 2022).
skin disorder (1 paper, 2021). Any deviation from the normal structure or function of the skin or subcutaneous tissue that is manifested by a characteristic set of symptoms and signs. "ACVR1C may be a target for preventing or treating UV-induced disruptions in lipid metabolism and associated skin disorders." (PMID 33499275, 2021).
ACVR1C also shares sentences with these, for which no sentence is quoted: Insulin resistance (6 papers); ovarian carcinoma (6); myeloma (4); Glucose intolerance (3); metabolic disease (3); cardiac hypertrophy (2); hepatocellular carcinoma (2); Hyperinsulinemia (2); Ventricular arrhythmia (2); acquired long QT syndrome (1); Arrhythmia (1); atherosclerosis (1); atrioventricular block (1); bladder tumors (1); Cachexia (1); Cognitive impairment (1); COVID-19 (1); depression (1); fibrosis (1); Genetic obesity (1); glucose metabolism disorder (1); Hyperkeratosis (1); hypertriglyceridemia (1); hypertrophic cardiomyopathy (1); Impaired glucose tolerance (1); lipodystrophy (1); melanoma (1); mesothelioma (1); metabolic syndrome (1); oral cancers (1).
A further 4 diseases each share a sentence with ACVR1C in 1 paper.